COMT (catechol-O-methyltransferase)
Diseases named in the same sentence as COMT in open-access papers (continued):
Sharing a sentence is not in itself a finding about the gene and the disease.
Parkinson disease (continued). "COMT is considered a target for study and development of new anti-Parkinson drugs using coadministration with levodopa." (PMID 30693065, 2018). "Tolcapone is FDA approved in adult patients for the treatment of Parkinson's disease (PD) as an adjunct therapy with levodopa 17, which is a dopamine precursor and is metabolized by COMT." (PMID 28429453, 2017). "Tolcapone, a drug commonly used in the treatment of Parkinson's disease, is a potent inhibitor of COMT and previous studies indicate that Tolcapone increases the bioavailability of dopamine in cells." (PMID 28429453, 2017). "We sought to define how the early cognitive deficits in newly diagnosed patients with Parkinson’s disease map onto changes in brain activation, and how these activations in patients varied as a function of the common genetic variations in COMT, MAPT and APOE." (PMID 25080285, 2014). "The COMT inhibitor tolcapone has been used clinically in Parkinson's patients to effectively treat their effort-related depressive symptoms." (PMID 24937131, 2014). "COMT inhibitors are used as an adjunctive treatment for Parkinson's disease, as they increase central L-DOPA availability." (PMID 23613951, 2013). "Given the use of COMT inhibitors for Parkinson's disease, the impact of tolcapone on dopamine levels has been well-studied in the striatum." (PMID 23613951, 2013). "COMT inhibitors are licensed for the adjunctive treatment of Parkinson's disease and are attractive therapeutic candidates for other neuropsychiatric conditions." (PMID 23613951, 2013). "A variety of drugs have been developed in the last fifty years and are currently used to control the disability related to Parkinson's disease (PD): levodopa, dopamine-agonists, monoaminoxidase B inhibitors, catechol-O-methyltransferase inhibitors." (PMID 22701812, 2012). "A further important trial on the efficacy of COMT inhibition with EN was the FIRST-STEP (Favorability of Immediate-Release Levodopa/Carbidopa vs STalevo Short-Term comparison in Early Parkinson’s disease) study." (PMID 23211041, 2012). "Significantly elevated erythrocyte COMT activity has been reported in patients with anxiety states and COMT inhibitors are effectively used in the treatment of anxiety symptoms in Parkinson's disease." (PMID 22745815, 2012). "Intriguingly, both COMT and MAO inhibitors cause significant modulating effects on the clinical manifestations of Parkinson's disease." (PMID 20976142, 2010). "In addition, COMT inhibitors are the least well-known medication, despite having a long history of clinical use since 1998 (First COMT inhibitor approved for Parkinson's disease, 1998)." (PMID 40271184, 2025). "Similarly a 39‐week study with the levodopa/carbidopa/entacapone (LCE) combination showed a significant difference in total Unified Parkinson's Disease Rating Scale (UPDRS) scores in favor of the COMT inhibitor arm versus traditional levodopa/DDCI therapy." (PMID 39790009, 2025). "This longitudinal study, which explores the genetic influence of COMT gene variations on four-year temporal changes in cortical thickness in Parkinson's disease, has provided valuable insights into the complex interplay between genetics and neurodegenerative processes." (PMID 38689006, 2024). "COMT is a target enzyme of Parkinson’s disease and depression." (PMID 36770999, 2023). "Opicapone is a long-acting, third generation selective catechol‐o‐methyl transferase (COMT) inhibitor, which became available in Europe in 2016 and is indicated as adjunctive treatment to levodopa in people with Parkinson's disease (PwP) who experience motor fluctuations." (PMID 37036498, 2023). "Catechol-O-methyltransferase (COMT) inhibitors are drugs used to treat Parkinson's disease." (PMID 37841347, 2023). "In addition, this scaffold is a crucial component of salient human catechol-O-methyltransferase (hCOMT) inhibitors such as entacapone, which are clinically applied for the treatment of Parkinson’s disease." (PMID 37515225, 2023).
Parkinson disease (continued). "Although entacapone, the inhibitor of COMT, is commercially available for the treatment of Parkinson’s disease and a few patients exhibit the onset of clinical apparent liver damage, this may be due to the short duration of this medication." (PMID 35057469, 2022). "Currently, Parkinson’s disease treatment relies on a triple prophylaxis, involving dopamine replacement by levodopa, the use of aromatic L-amino acid decarboxylase inhibitors, and the use of COMT inhibitors." (PMID 36293152, 2022). "However, the more cytosolic dopamine, 6-OHDA is more likely to occur, especially if dopamine metabolism is affected by MAO or COMT inhibitors, drugs used in Parkinson’s disease treatment." (PMID 33918172, 2021). "Parkinson’s Disease medications used included levodopa and decarboxylase inhibitor (74%), pramipexole (12.2%), ropinirole (3.8%), entacapone (3.3%), amantadine (2.8%), selegiline (2.0%), and levodopa, decarboxylase inhibitor and COMT inhibitor (1.1%)." (PMID 33964882, 2021). "Therefore, the promising results obtained, combined with the structure similarity with commercial COMT inhibitors, can allow for the future development of a potential new Parkinson’s disease drug candidate with improved properties." (PMID 35056108, 2021). "Inhibitors for COMT are thus used to treat Parkinson’s disease together with the dopamine precursor L–DOPA; the goal is to prevent dopamine deficiency in neurons, and the role of COMT inhibitors is to avoid L–DOPA degradation before it is converted to dopamine." (PMID 34681286, 2021). "Available evidence suggests that medication used for the symptomatic improvement of parkinsonism in people with PD, especially catechol-O methyltransferase inhibitors, may also interfere with the composition of the gut microbiota." (PMID 34769091, 2021). "In addition, recent studies have shown that tolcapone, a catechol-O-methyltransferase inhibitor used in Parkinson’s disease, decreases cell viability in lung cancer and neuroblastoma cell lines." (PMID 36303724, 2021). "Inhibitors of COMT are clinically used for the treatment of Parkinson’s disease." (PMID 34030574, 2021). "Therefore, Tolcapone, a potent COMT inhibitor to treat Parkinson’s disease, was reported in neuroblastoma cell lines to induce oxidative stress leading to caspase-3-mediated apoptosis and to inhibit tumor proliferation." (PMID 33465163, 2021). "COMT inhibitors had been used to ameliorate symptoms of parkinson’s disease (Müller 2015)." (PMID 27917343, 2016). "Catechol‐O‐methyltransferase (COMT), an important therapeutic target in the treatment of Parkinson's disease, is also being developed for biocatalytic processes, including vanillin production, although lack of regioselectivity has precluded its more widespread application." (PMID 26797714, 2016). "Specifically, the best documented is the important role that COMT plays in Parkinson’s disease whose most effective treatment remains the dopamine replacement therapy with levodopa together with an inhibitor of aromatic amino acid decarboxylase and a COMT inhibitor." (PMID 26246150, 2015). "Since rifampin inhibits DNA-dependent RNA polymerase, this observation implies cross-reactivity between the M.tuberculosis InhA, the target of isoniazid, and the drug targets of Parkinson's disease, which is consistent with our predictions that InhA inhibitors can also inhibit COMT." (PMID 19578428, 2009). "Therefore, it may be a promising drug candidate for the development of COMT inhibitors useful in the treatment of Parkinson’s disease." (PMID 37049962, 2023). "However, they may also include neuroplasticity consequences of COMT, APOE and MAPT functional polymorphisms in the context of Parkinson’s disease pathogenesis, or developmental effects even if these diminish with older age (e.g. for COMT)." (PMID 25080285, 2014).
Parkinson disease (continued). "Bei Patienten mit Morbus Parkinson werden häufig Levodopa (L-Dopa), Dopaminagonisten, MAO-B-Hemmer, Catechol-O-Methyltransferase (COMT)-Inhibitoren N‐Methyl-D-Aspartat (NMDA)-Antagonisten und Anticholinergika eingesetzt." (PMID 38700730, 2024). "Inhibitors of monoamine oxidase B (MAO-B) and catechol-O-methyltransferase (COMT) are major strategies to reduce levodopa degradation and thus to increase and prolong its effect in striatal dopaminergic neurotransmission in Parkinson’s disease patients." (PMID 36964457, 2023). "Entacapone, a specific inhibitor of catechol-O-methyltransferase (COMT), has long been used as an adjuvant therapy for Parkinson’s disease." (PMID 36358568, 2022). "Positive correlation between COMT and HVA is lost in Parkinson’s disease olfactory bulbs." (PMID 40024917, 2025). "The purpose of the present study was to identify the major compounds in C. officinalis leaves and to determine the inhibitory properties of the isolated compounds toward human catechol-O-methyltransferase (COMT), a key neurotransmitter involved in Parkinson’s disease and depression." (PMID 36770999, 2023). "6,7-Dihydroxy-1-methyl-1,2,3,4-tetrahydroisoquinoline-1,3-dicarboxylic acid (B), isolated from Mucuna pruriens, traditionally used for the treatment of Parkinson’s disease, and synthetized from L-DOPA, behaves as a peripheral catechol-O-methyltransferase inhibitor (COMTI)." (PMID 37049962, 2023). "Catechol-O-methyltransferase (COMT) has been involved in a number of medical conditions including catechol-estrogen-induced cancers and a great range of cardiovascular and neurodegenerative diseases such as Parkinson’s disease." (PMID 36293152, 2022). "There were no global or local interactions between Parkinson's disease and COMT val158met genotype on morphometry." (PMID 18755526, 2010). "Both COMT and MAO inhibitors have found clinical utility in Parkinson's disease." (PMID 20976142, 2010). "Levodopa (LD), the most effective drug for Parkinson’s disease treatment, has poor oral availability; therefore, it is taken concomitantly with inhibitors of LD-metabolizing enzymes, including dopa deoxycarboxylase (DDC) and catechol-O-methyltransferase (COMT)." (PMID 40693278, 2025). "The initial generation of COMT inhibitors was excessively toxic to be approved for use, but second-generation COMT inhibitors, including tolcapone (TOL), have been found to be effective in providing symptomatic relief for certain Parkinson’s patients with an acceptable toxicity profile." (PMID 38544890, 2024). "Opicapone provides beneficial motor and nonmotor effects in Emirati and other non-White Parkinson’s patients, resident in UAE, proving its efficacy across different racial groups as COMT activity may vary between races." (PMID 37798410, 2024).
depression (117 papers, 2006 to 2026). "In a review of the role of COMT gene variants in depression, most studies focusing on the difference between depressed patients and HCs did not detect significant results." (PMID 39202218, 2024). "More recent reports have attempted to differentiate the association between COMT polymorphisms, pain, and depression in PD cohorts." (PMID 39338193, 2024). "Logistic regression model testing the simultaneous influence of age, sleep impairment, depression, and COMT Val158Met (rs4680) genotypes on the risk of having fibromyalgia." (PMID 38916531, 2024). "Studies of major depression and anxiety show a similar inconclusiveness concerning the distribution of the COMT gene polymorphism." (PMID 39202218, 2024). "In Chinese Han populations, COMT rs4818 and rs4680 have been associated with susceptibility to treatment-resistant depression." (PMID 39338193, 2024). "Last but not least, the valine to methionine replacement at codon 158 (Val158Met) polymorphism in the catechol-O-methyltransferase (COMT) gene has been linked stress leading to diseases such as depression and anxiety in adults." (PMID 39628897, 2024). "This study aimed to investigate associations between anxiety/depression/chronic pain and oral health-related quality of life (OHRQoL)/happiness/polymorphisms in the COMT, HTR2A and FKBP5 genes in Brazilian adolescents." (PMID 36834016, 2023). "The COMT Val158Met polymorphism has been implicated in various psychiatric disorders, including depression, anxiety, and schizophrenia." (PMID 37239455, 2023). "The presence of minor allele C of COMT rs174675 was significantly associated with depression (p = 0.040)." (PMID 36834016, 2023). "The COMT gene moderates the association between depression and SLEs as Val158 allele homozygote patients experiencing SLEs had the highest level of depressive symptoms compared to the others (p = 0.002)." (PMID 36833277, 2023). "This study evaluated anxiety, depression and chronic pain in adolescents as well as associations with oral health-related quality of life, feelings of happiness and polymorphisms in the COMT, HTR2A, and FKBP5 genes." (PMID 36834016, 2023). "Our findings suggest that high COMT activity related to low dopamine availability was associated with the lowest anxiety and depression dimension scores in males." (PMID 37510262, 2023). "Treatment with COMT inhibitors was associated with relatively improved depression symptoms as the disease progressed (β=−0.37, 95%CI [−0.72, −0.01], p=0.041), but worse symptoms on average across all years of follow up (β=2.2, 95%CI[0.43, 4.1], p=0.015)." (PMID 37425947, 2023). "Several studies have reported that the COMT mutation is associated with the response to anxiety, depression, and Alzheimer’s disease." (PMID 36405903, 2022). "In children without morphological signs of FASD who carried the minor A allele of the COMT rs4680:G > A polymorphism, the clinical picture was more often associated with emotional anxiety and/or depressive disorders, and MPH was the drug of choice." (PMID 35457347, 2022). "The study found that the rs4680 variant of the COMT genotype was associated with AD, and the rs174696 variant of COMT was associated with depression in Greek AD patients." (PMID 34725583, 2021). "The rs4680 variant of the COMT genotype was associated with AD, and the rs174696 variant of COMT was associated with depression in Greek AD patients." (PMID 34725583, 2021). "Improvement in neurocognitive function was seen following tDCS treatment in patients with depression, and it was found that COMT rs4680 variant affected verbal fluency outcomes." (PMID 34725583, 2021). "Although there were a few studies reporting an interaction between the COMT Val158Met polymorphism and childhood abuse, they have focused on major depressive disorder, bipolar disorder, anxiety disorders, schizophrenia, and other related disorders." (PMID 32618128, 2020).
depression (continued). "The identity of the at risk allele has varied between studies, although a meta-analysis demonstrated high activity COMT Val allele as risk allele for depression." (PMID 30045690, 2018). "The degree of this improvement positively correlated with subjective measures of stress, depression, and alcohol consumption and was most robust in carriers of the COMT Val158 allele." (PMID 30027496, 2018). "Catechol-O-methyltransferase (COMT Val158Met) has been implicated in both depression and cardiovascular disease." (PMID 30045690, 2018). "Because of previous gender-specific associations for COMT Val158Met with depression and CVD we performed gender-stratified analyses." (PMID 30045690, 2018). "The COMT Val158Met genetic variation influencing COMT enzyme activity has previously been associated with risk for depression, and risk for CVD." (PMID 30045690, 2018). "Another study also revealed that women with MAOA and COMT low-activity alleles scored higher for postpartum depression symptoms." (PMID 30018578, 2018). "Our findings suggested that, in addition to depression, genetic variants of COMT rs6267 and rs4680 can also modulate pain sensitivity in patients with PD." (PMID 28740224, 2017). "To further clarify the contribution of depression and COMT SNPs to pain susceptibility and perception intensity in PD patients, we stratified the analyses by participants’ status of depression." (PMID 28740224, 2017). "In a large multi-centred study, an association was found between the high-activity COMT Val allele, particularly the COMT Val/Val genotype, and early onset depression." (PMID 29019461, 2017). "We stratified PD by status of depression and the association between COMT rs6267 “GT” genotype and pain severity remained significant (P < 0.01)." (PMID 28740224, 2017). "The COMT rs6267 “GT” genotype was associated with increased pain intensity in patients with PD with pain, even after stratified by depression status." (PMID 28740224, 2017). "Depression is an important psycho-affective contributor to the susceptibility of pain in a general population and SNPs of COMT gene are also reported to associate with depression." (PMID 28740224, 2017). "Significant associations between DRD2, DRD4, and COMT polymorphisms and the risk of depression, as well as the severity of depressive symptoms, were reported." (PMID 26733829, 2015). "Variations in the COMT gene exert complex effects on susceptibility to depression through various intermediate phenotypes, such as impulsivity and executive function." (PMID 25266489, 2014). "Previously, functional polymorphisms in the monoamine oxidase gene (rs6323 G-allele at MAOA) and the COMT (Met allele at Val158Met) predicted reduced placebo responses in depression." (PMID 25222607, 2014). "Association studies of the COMT Val158Met polymorphism with respect to affective disorders, in particular depression, are similarly inconclusive." (PMID 22745815, 2012). "The aim of the present study was to examine the relationship between the Val158Met COMT gene polymorphism and anxiety and depression measured by the Hospital Anxiety and Depression Scale (HADS) in the general adult population." (PMID 18578865, 2008). "The COMT gene encodes catechol-O-methyltransferase and is involved in the regulation of the dopamine metabolism network, it is involved in treatment-resistant depression, borderline personality disorder, post-traumatic stress disorder, and other mental disorders." (PMID 38203806, 2024). "Depression may influence different gene polymorphisms, including COMT, ADRB2, and HTR1A genes, which are associated with chronic joint pain and TMD." (PMID 38836036, 2024). "Therefore, in this study we investigated the association between anxiety/depression/chronic pain and OHRQoL/feelings of happiness/polymorphisms in the COMT, HTR2A, and FKBP5 genes in Brazilian adolescents." (PMID 36834016, 2023).